CLDN11 (claudin 11)
Diseases named in the same sentence as CLDN11 in open-access papers (continued):
Sharing a sentence is not in itself a finding about the gene and the disease.
tumor (continued). "In addition to cell barrier functions, CLDN11 appears to have a tumor suppressor function." (PMID 29747653, 2018). "Thus, CLDN11 is a bona fide tumor suppressor gene, which can be inactivated by DNA methylation." (PMID 29747653, 2018). "Compared to tumors with diploid/normal copy number, levels of B cell and CD4+ T cell infiltration were reduced in tumor samples with arm-level deletion of BTLA, CLDN11, and FGF5." (PMID 39796775, 2025). "Since CLDN7, CLDN11 and CD274 correlate with the invasive and metastatic ability of tumours, we further did Wound healing assays and transwell assays." (PMID 38575994, 2024). "Tumor purity, another substantial parameter for the tumor microenvironment, is negatively correlated with CLDN5, CLDN11, and CLDN18 (Absolute value of Spearman Correlation is 0.20 and p < 0.001)." (PMID 37799140, 2023). "Previous studies exploring the effects of CLDN1, CLDN2, CLDN4, CLDN11, CLDN12, CLDN14, and CLDN23 expression on CRC tumor growth have yielded findings consistent with our results in the present study." (PMID 35281827, 2022). "Significant differences in CLDN3, CLDN4, CLDN5, CLDN6, CLDN9, CLDN11, and CLDN12 expression were evident as a function of tumor stage." (PMID 35281827, 2022). "Using the TIMER database, we detected a negative correlation between the mRNA level expression of CLDN5, CLDN8, CLDN11, and CLDN18 and CRC tumor purity." (PMID 35281827, 2022). "At the mRNA level, we found that CLDN11 and CLDN4 expression were respectively reduced and increased in CRC tumor samples relative to paracancerous controls as measured via qPCR (n = 10, p < 0.05)." (PMID 35281827, 2022). "Relative to paracancerous tissues, clinical CRC tumor tissue samples exhibited CLDN4 and CLDN11 upregulation and downregulation, respectively." (PMID 35281827, 2022). "Therefore, we assessed the methylation frequency of CLDN11 in 125 CRC samples, and analyzed the associations between aberrantly methylated CLDN11 and the progression of CRC, along with other clinical characteristics, such as gender, age, tumor size and differentiation." (PMID 29221203, 2017). "CLDN11 belongs to a family of claudins that are highly expressed in some cancers and play an important role in tight junction-initiated epithelial-mesenchymal transition (EMT), which mediates tumor cell migration." (PMID 41551611, 2025). "Amh, marking immature Sertoli cells, was not detectable in our RNAseq dataset, while levels of mature Sertoli cells markers, Gata1 and Cldn11, were not different compared to WT, indicating the tumour cells had not acquired an immature Sertoli cell signature." (PMID 37564373, 2023). "Claudin-11 mRNA levels were not different between carcinogenic and control samples; however, claudin-11 staining was less in the tumor samples when using immunohistochemistry." (PMID 38188015, 2023). "In addition to the reduction in CLDN11 expression, NPC tumor cells were morphologically distinct from the normal epithelial cells, becoming disorganized and having irregular cell boundary with large nuclei." (PMID 29747653, 2018). "To investigate the differentially methylated CpG sites of the CLDN11 promoter in clinical samples, we performed bisulfite sequencing analysis of seven paired tumor and nontumor genomic DNA ranging from − 137 to + 405 containing 52 CpG sites." (PMID 29747653, 2018). "However, CLDN11 expression was low and diffusely located in the cytoplasm of NPC tumor tissues." (PMID 29747653, 2018).
cancer (31 papers, 2009 to 2025). A tumor composed of atypical neoplastic, often pleomorphic cells that invade other tissues. "Abnormal claudin-11 function has been implicated in various pathologies ranging from cancer to behavioral and myelin abnormalities, and most notably the hypomyelinating disorder HLD22." (PMID 38298375, 2023). "For example, in gastric cancers, hypermethylation of CLDN11 and downregulation of its expression were associated with increased cancer cell motility and invasiveness." (PMID 38298375, 2023). "Conversely, studies investigating epithelial-mesenchymal transition (EMT) mechanism implicated in cancer metastasis report increased expression of CLDN11 correlating with less favorable patient outcomes." (PMID 38298375, 2023). "Methylation of CLDN11 promoter is known to be associated with the development and poor survival in several cancers." (PMID 33714203, 2021). "For CLDN11 it has been reported that it is silenced in gastric cancer by promoter hypermethylation and its inactivation is associated with invasiveness of this cancer." (PMID 26198249, 2015). "Outside normal physiology, claudin-11 expression has been implicated in several cancer types." (PMID 38298375, 2023). "Interestingly, both claudin-11 silencing and overexpression have been linked to invasiveness of cancer cells." (PMID 38298375, 2023). "Altogether, loss of CLDN11/OSP, to which miR-92a-3p contributes, is considered a mechanism for the disruption of cell adhesion and increased cell motility, which are important processes not only in cancer progression and metastasis but also in angiogenesis." (PMID 31500278, 2019). "Interestingly, siRNA-mediated downregulation of CLDN11 in CLDN11-expressing gastric cells was also associated with cancer-related phenotypic changes, specifically increased cell motility and invasiveness." (PMID 19956721, 2009). "Altogether, it indicates that the expression of CLDN5, CLDN11, CLDN2, CLDN7, and CLDN12 is associated with regulating the key cancer-associated pathways in the COAD and GSEA datasets." (PMID 37799140, 2023). "Another explanation is that both CLDN1 and CLDN11 induce chemoresistant characteristics of cancer cells." (PMID 31551535, 2019). "This indicates that aberrant hypermethylation of CLDN11 promoter frequently occurs near the transcription start site in different cancers." (PMID 29747653, 2018). "Regardless of the detection method used, the general expression trend of claudin-11 and 23 was quite consistent between cancer tissues and adjacent tissues." (PMID 28350854, 2017). "The result was consistent between WB and IHC in cancer tissues for claudin-23 expression (kappa = 0.854, P = 1.12*10−10) and marginally consistent for claudin-11 expression (kappa = 0.203, P = 0.011)." (PMID 28350854, 2017). "Notably, we establish, at the best of our knowledge, for the first time a statistical correlation between the downregulation of CLDN11 and poor prognosis in this cancer type." (PMID 40083695, 2025). "Moreover, CLDN7 and CLDN11 play cancer-promoting roles in the pathogenesis of CRC, whereas CLDN6 plays a cancer-promoting role in the pathogenesis of GC." (PMID 38201579, 2023). "In contrast, claudin-11 upregulation in EMT-linked cancers may promote maintenance of cell clusters, thus facilitating more efficient cancer cell dissemination." (PMID 38298375, 2023). "Low CLDN11 expression has been used as a prognosis biomarker in certain cancers." (PMID 33714203, 2021). "Tubulin polymerization inhibitors may be used to block migration in cancer cells, which have low CLDN11 expression." (PMID 29747653, 2018). "Previous studies reported that claudin-11, -23 are abnormally expressed in many malignant tumors." (PMID 28350854, 2017). "Previous studies found that claudin-11, -23 are expressed abnormally in several malignant tumors." (PMID 28350854, 2017). "Methylation of CLDN11 was also observed in A549 and HeLa cancer cells." (PMID 26198249, 2015).
cancer (continued). "Cells were positive for claudin-11 in 46.4% (13/28) of tissues adjacent to the cancer." (PMID 23919729, 2013). "Interestingly, CLDN11 shows dramatic under-expression in cancer, especially in samples with this amplicon." (PMID 19419571, 2009). "In addition, cancer cells may induce claudin-11 overexpression and subsequent collective migration of peritumoral carcinoma−associated fibroblasts (CAFs) via TGF-β secretion." (PMID 34354941, 2021). "We speculate that the interaction between CLDN11 and the two tubulins may modulate microtubules remodeling, possibly influencing the cytoskeleton rearrangement, directional migratory effect, cell motility, and cell cycle in cancer cells." (PMID 29747653, 2018). "A population-wide examination of TT and LN single cells found that primary cancer overexpresses NOTCH2, NOTCH2NL, KIF5B, and ERBB4 but that metastatic cancer overexpresses CDK12, ERBB2, and CLDN11." (PMID 37322261, 2024). "Gene differential expression analysis revealed that cancer cell subgroup 1 was characterized by high expression of genes such as TMEFF2, subgroup 2 by high expression of genes such as RGS1, and subgroup 3 by high expression of genes such as CLDN11." (PMID 40843359, 2025). "In addition to these, we also identified some novel genes among the 14-CpG markers that were not previously associated with cancer recurrences such as IFFO1, ALKAL1, FAHD1, FSTL4, SLC7A9, IQCJ-SCHIP1, CLDN11 and three other CpGs at intergenic regions." (PMID 34207933, 2021). "Thus, CLDN11 may serve as prognostic and potential therapeutic biomarker for NPC and other cancers." (PMID 29747653, 2018). "Several genes that were highly expressed in Cluster 3 were well known to be preferentially expressed in normal oligodendrocytes, including CLDN11, MBP, PLP1, and KLK6, indicating that these cells are not cancer cells." (PMID 27368803, 2016).
infection (8 papers, 2017 to 2025). The state of being infected such as from the introduction of a foreign agent such as serum, vaccine, antigenic substance or organism. "In addition, in EcN + C. jejuni, the expression of the CLDN2, CLDN4, and CLDN11 encoding genes was down-regulated in comparison to infection with C. jejuni." (PMID 28878749, 2017). "In addition, in EcN + C. jejuni, the expression of the CLDN2, CLDN4, and CLDN11 encoding genes was up-regulated in comparison to infection with C. jejuni." (PMID 28878749, 2017). "Among tight junction-associated genes, CLDN11 was downregulated in both infections at 24 hpi, whereas CLDN16 and CLDN18 were specifically downregulated following Delta infection." (PMID 41200555, 2025). "In the intestinal tract, the overexpression of Claudin 10 or the insufficient expression of Claudin 11 is usually induced by pathogen infection and considered as a sign of intestinal damage." (PMID 38137937, 2023). "Our previous studies showed that the mRNA expression levels of tight junctions including claudin-1, claudin-3, claudin-7, and claudin-11 were up-regulated with AKG supplementation after infection with A. hydrophila." (PMID 35720284, 2022). "The mRNA levels of claudin-1, claudin-3, claudin-7, claudin-11, occludin and ZO-1 were all downregulated in the case of infection with A. hydrophila (P < 0.05)." (PMID 34220849, 2021). "We also detected a discrete reduction of ZO-1 (encoded by Tjp1) expression upon infection, without change and in the levels of Claudin-2 and Claudin-11." (PMID 35027063, 2022). "In contrast, compared with infection groups, AKG supplementation could significantly upregulate the gene expression levels of claudin-1 and claudin-3, and as well as the mRNA level of claudin-7 and claudin-11 (P < 0.05)." (PMID 34220849, 2021).
CLDN11 also shares sentences with these, for which no sentence is quoted: schizophrenia (2 papers); acute pancreatitis (1); auditory neuropathy (1); autism spectrum disorder (1); autosomal recessive deafness (1); bipolar affective disorder (1); cervix cancer (1); colitis (1); colon adenocarcinoma (1); congenital heart disease (1); dysplastic nevi (1); E. coli infection (1); edema (1); endometrioid endometrial carcinoma (1); esophageal carcinoma (1); experimental autoimmune encephalomyelitis (1); gastric adenocarcinoma (1); gastric disease (1); hypothyroidism (1); infantile hemangiomas (1); invasive ductal breast carcinoma (1); ischemic stroke (1); Klinefelter syndrome (1); laryngeal squamous cell carcinoma (1); Leukoencephalopathy (1); malignant melanoma of the skin (1); metastasis (1); movement disorder (1); myocardial infarction (1); neurological disorders (1).
A further 6 diseases each share a sentence with CLDN11 in 1 paper.